MIR769 (microRNA 769)
Synonyms: hsa-mir-769; MIRN769; mir-769
Gene: MicroRNA gene on chromosome 19 (46,018,932 to 46,019,049, forward strand). Ensembl gene ENSG00000211580.
Homologues: Orthologues: chimpanzee MIR769 (100% identical).